LMNA (lamin A/C)
Diseases named in the same sentence as LMNA in open-access papers (continued):
Sharing a sentence is not in itself a finding about the gene and the disease.
laminopathies (continued). "Laminopathies are a class of rare genetic disorders that are characterized by de novo heterozygous mutations in the lamin A (LMNA) gene." (PMID 36225129, 2022). "Mutations that disrupt the production of normal lamin proteins that is encoded by the LMNA gene cause a group of human disorders collectively called laminopathies." (PMID 35348702, 2022). "Clusters of mutations corresponding to different laminopathies were also found at different exons of the LMNA gene." (PMID 36552829, 2022). "Mutations in the LMNA gene encoding lamins A and C cause a heterogenous group of inherited degenerative diseases known as laminopathies." (PMID 36111332, 2022). "Although the globular domain is a hotspot for laminopathy‐associated mutations, structural destabilization of LMNA is also driven by mutations in the rod domains of the protein." (PMID 36225129, 2022). "These syndromes caused by mutations in the LMNA gene encoding A-type lamins belong to a group of disorders called laminopathies." (PMID 36104080, 2022). "Numerous mutations have been found throughout the LMNA gene that causes a spectrum of human genetic disorders, collectively called laminopathies." (PMID 36301259, 2022). "Dunnigan syndrome belongs to the group of laminopathies, which are rare diseases related to pathogenic variants in the LMNA gene encoding type A lamins." (PMID 35440056, 2022). "Mutations in the lamin A/C (LMNA) gene cause laminopathies, a group of disorders characterized by phenotypically heterogeneous manifestations." (PMID 34969177, 2022). "In the present study, we used induced pluripotent stem cells from a patient carrying LMNA p.R249Q genetic variant to create an in vitro cardiac model of laminopathy." (PMID 35935653, 2022). "Several hundred LMNA gene mutations have been linked to at least four different disease groups, collectively called laminopathies." (PMID 36362411, 2022). "Classical laminopathy refers to diseases caused by mutations in LMNA coding for lamin A/C, key components forming the intermediate filaments of the nuclear lamina." (PMID 36555163, 2022). "Mutations or expression alterations of LMNA have been proven to be closely related to laminopathies and cancer." (PMID 35977926, 2022). "Mutations in the lamin A/C gene (LMNA) cause laminopathies such as the premature aging Hutchinson Gilford progeria syndrome (HGPS) and altered lamin A/C levels are found in diverse malignancies." (PMID 36099415, 2022). "More than half of laminopathies are caused by LMNA gene mutations, in which HGPS is the thoroughly studied one that is caused by heterozygosity for LMNA point mutations, such as the canonical G608G mutation." (PMID 35656549, 2022). "Classical laminopathy comprises a large number of mutations in LMNA, with more than 300 likely pathogenic and pathogenic variants reported in the ClinVar database." (PMID 36555163, 2022). "Pathogenic variants in the LMNA gene are known to cause laminopathies, a broad range of disorders with different clinical phenotypes." (PMID 35935653, 2022). "Here, we review the clinical phenotypes of various laminopathies and explore the epigenetic and chromatin-related consequences of LMNA disease-linked mutations." (PMID 36503349, 2022). "Deleterious, mostly de novo, mutations in the lamin A (LMNA) gene cause spatio‐functional nuclear abnormalities that result in several laminopathy‐associated progeroid conditions." (PMID 36225129, 2022). "Patient HGPS-L2, carrying the heterozygous LMNA c.1968+1G>A mutation, showed a very similar progeroid laminopathy, though evolving more severely." (PMID 35203262, 2022). "DSP and LMNA pathogenic genetic variants are known to cause arrhythmogenic and dilated cardiomyopathy or laminopathy, respectively." (PMID 35348702, 2022). "Mutations in the LMNA gene, encoding A-type lamins, are known to cause heredity diseases with a wide range of phenotypes—laminopathies." (PMID 35935653, 2022).
laminopathies (continued). "Several mutations within the LMNA gene have been associated with diseases that are collectively referred to as laminopathies." (PMID 35414260, 2022). "Hundreds of mutations in LMNA, the gene encoding Lamin A/C, have been identified as causing degenerative disorders, collectively called laminopathies, an example of which is Hutchinson–Gilford Progeria Syndrome (HGPS)." (PMID 33964983, 2021). "Mutations in the A-type lamin gene (LMNA) manifest as tissue-specific degenerative diseases (laminopathies) with varied clinical symptoms that include dilated cardiomyopathy, atherosclerosis, muscular dystrophy, lipodystrophy, neuropathy and progeria." (PMID 33802236, 2021). "Over the past 20 years, it has been found that most laminopathies are caused by mutations in the LMNA gene, which encodes lamin A/C." (PMID 34722546, 2021). "More than 400 mutations in LMNA have been attributed to at least 11 diseases, which are collectively termed laminopathies." (PMID 34385357, 2021). "HGPS belongs to a group of diseases called laminopathies, all of them sharing mutations in the LMNA gene as the causal agent." (PMID 34298947, 2021). "More than 400 distinct mutations in the LMNA gene are associated with over 17 different disease phenotypes known as laminopathies." (PMID 34298968, 2021). "Over the past two decades many disorders have been linked to LMNA variants, collectively termed laminopathies." (PMID 33033404, 2021). "Mutations in LMNA are associated with premature aging syndromes and muscular dystrophies, collectively termed as laminopathy." (PMID 33413510, 2021). "HGPS belongs to a broader group of diseases called laminopathies, which are a consequence of different mutations in the LMNA gene." (PMID 34281245, 2021). "As such, in laminopathy, cells with mutations in the LMNA gene have a weaker nuclear envelope and are more susceptible to ruptures." (PMID 34298904, 2021). "The rapamycin analogue, everolimus, also has a demonstrated beneficial effect on the phenotype of cell lines derived from patients with various laminopathies caused by mutations in LMNA." (PMID 34453483, 2021). "Mutations in LMNA, encoding lamin A/C, lead to a variety of diseases known as laminopathies including dilated cardiomyopathy (DCM) and skeletal abnormalities." (PMID 34246298, 2021). "Laminopathies are a heterogeneous group of inherited disorders caused by mutations in the LMNA gene." (PMID 33803191, 2021). "Pathogenic variants in the LMNA gene cause a group of heterogeneous genetic disorders, called laminopathies." (PMID 34680903, 2021). "Over 500 mutations, mainly dominant, have been identified throughout the LMNA gene and linked to a broad spectrum of diseases called laminopathies." (PMID 34768351, 2021). "Mutations in lmna gene encoding intermediate filament proteins of the inner nuclear membrane Lamin A/C (LMNA) cause tissue‐specific systemic diseases collectively known as laminopathies." (PMID 34773379, 2021). "Laminopathies are disorders caused by LMNA gene mutations, which selectively affect different tissues and organ systems, and present with heterogeneous clinical and pathological traits." (PMID 33803191, 2021). "Due to the high risk of SCD that characterizes patients with lamin A/C cardiomyopathy, genetic testing for LMNA gene variants is highly recommended when there is suspicion of laminopathy." (PMID 34768595, 2021). "Laminopathies are a heterogeneous group of disorders caused by mutations in the LMNA gene encoding lamin A/C." (PMID 34240052, 2021). "Laminopathies are a family of monogenic multi-system diseases resulting from mutations in the LMNA gene which include a wide range of neuromuscular disorders." (PMID 32906763, 2020). "Laminopathies are a group of human rare diseases mainly associated with different mutations on the Lamin A/C gene (LMNA)." (PMID 32455813, 2020).
laminopathies (continued). "The laminopathies caused by mutations in LMNA present abnormalities in postmitotic tissues, such as muscle, nerve, heart, and adipose tissues." (PMID 31833196, 2020). "Although Lamin A/C is expressed in most differentiated cell types, LMNA mutations predominantly affect mesoderm-derived cell lineages in diseases collectively termed as laminopathies." (PMID 32698886, 2020). "The term “laminopathies” comprehend 16 rare disorders that have mutations in LMNA as a common characteristic." (PMID 32854405, 2020). "Mutations in the LMNA gene cause laminopathies, a highly heterogeneous group of disorders, including muscular dystrophies and cardiomyopathies." (PMID 32231000, 2020). "Laminopathies are inherited degenerative disorders that are mostly related to mutations in the LMNA gene." (PMID 31714004, 2020). "Variants in LMNA, encoding A-type lamins, are responsible for laminopathies including muscular dystrophies, lipodystrophies, and progeroid syndromes." (PMID 32245113, 2020). "Mutations in the LMNA gene cause laminopathies, a phenotypically diverse group of disorders, including muscular dystrophies and cardiomyopathies." (PMID 33396724, 2020). "In humans, mutations in LMNA or other nuclear lamina/envelope genes are responsible for a plethora of diseases termed laminopathies, which include muscular dystrophies, cardiomyopathy, lipodystrophies, and progeroid syndromes." (PMID 32151001, 2020). "Most forms of mixed laminopathy phenotypes with lipodystrophy and cardiomyopathy have been described in patients with non p.Arg482 LMNA pathogenic variants affecting different protein domains." (PMID 32245113, 2020). "Pathogenic variants in the LMNA gene are responsible for several rare clinical disorders collectively called laminopathies." (PMID 32245113, 2020). "Most laminopathies are due to mutations in the LMNA gene, encoding lamin A and lamin C as major splicing products." (PMID 32517247, 2020). "LMNA mutations affect cardiac tissue, muscle tissues, adipose tissues to precipitate several diseases collectively termed as laminopathies." (PMID 32453974, 2020). "Studies on patients and lamin A/C–deficient mouse models indicate that loss of function of lamin A/C proteins also develops some of the laminopathies, including muscular dystrophy, dilated cardiomyopathy (DCM), and Charcot–Marie–Tooth disorder, type 2 (CMT2)." (PMID 32479501, 2020). "Unfortunately, little is known about the exact mechanisms underlying the effects induced by the majority of the laminopathy-causing LMNA mutations." (PMID 32455813, 2020). "The disease-causing mutations in LMNA, leading to primary laminopathies, can affect the functions of both peripheral and the nucleoplasmic pool of lamin A, and/or change their respective localization." (PMID 32471220, 2020). "One of type 2 Charcot-Marie-Tooth disease, a neuropathy involving axon degeneration, results from inherited mutations in either mitochondrial proteins or lamin A/C, classified as laminopathy." (PMID 32344905, 2020). "Several other laminopathy-causing LMNA mutations also impair the correct configuration of LADs, although to different extents." (PMID 32481609, 2020). "Laminopathies are a heterogeneous group of rare diseases caused by genetic mutations in the LMNA gene, encoding A-type lamins." (PMID 33036437, 2020). "LMNA mutations have been identified in a heterogeneous spectrum of rare human diseases commonly known as “laminopathies” involving different tissues and multiple systems with features of accelerated aging." (PMID 32069980, 2020). "The first cellular pathophysiological observation in laminopathies was an abnormal nuclear morphology due to mutations in the LMNA gene." (PMID 32796718, 2020). "Until now, more than 600 laminopathy mutations have been found in the LMNA gene, affecting many different tissues." (PMID 32796718, 2020). "Since, ~ 500 mutations throughout the LMNA gene have been connected to ~ 15 diseases commonly called laminopathies." (PMID 32241294, 2020).
laminopathies (continued). "The laminopathies caused by mutations in the LMNA gene can be grouped into those that affect striated muscle, those that affect adipose tissue, those involving peripheral nerve systems, or those involving multiple systems with signs of accelerated aging." (PMID 32796718, 2020). "Even though plenty of LMNA mutations are linked to muscle dystrophies, data about skeletal muscle bioenergetics in laminopathies are very limited." (PMID 32906763, 2020). "Mutations in LMNA cause a group of diseases called laminopathies; 79% affect the heart and/or skeletal muscles." (PMID 33142761, 2020). "LMNA mutations are responsible for a wide range of diseases, termed laminopathies, which affect various tissues in an isolated (striated muscle, adipose tissue or peripheral nerve) or systemic (premature aging syndromes) fashion." (PMID 32244403, 2020). "This is demonstrated by the fact that loss of lamin A/C results in lethality in mice and that mutation of the LMNA gene leads to a wide variety of laminopathies." (PMID 33316938, 2020). "Diseases associated with LMNA mutations or lamin A processing alterations are gathered in a family of pathologies and called laminopathies." (PMID 32842478, 2020). "We identified two independent cases of laminopathy with novel heterozygous LMNA mutations, p.Asp300His and p.Asn466Lys." (PMID 32954377, 2020). "In particular, the understanding of the effects of LMNA mutations on cell mechanical properties is crucial for uncovering the mechanisms of the physiopathology of laminopathies and the associated MDs and cardiovascular diseases." (PMID 32842478, 2020). "Laminopathies are pathologies that are caused by mutations in the LMNA gene that encodes lamin A/C, or in genes that encode lamin-binding proteins." (PMID 32481609, 2020). "The vast majority of autosomal dominant type of the progeric laminopathies arise from the so-called “classical” mutation in the LMNA gene—this mutation causes HGPS." (PMID 30691039, 2019). "Hutchinson-Gilford progeria syndrome (HGPS) is one of the most severe disorders among laminopathies—a heterogeneous group of genetic diseases with a molecular background based on mutations in the LMNA gene and genes coding for interacting proteins." (PMID 30691039, 2019). "Laminopathies are a group of inherited conditions due to mutations in the LMNA gene, that encodes the nuclear envelope proteins lamin A and C, via alternate splicing." (PMID 31744510, 2019). "Laminopathies are rare diseases caused by mutations in LMNA or other nuclear envelope genes or in genes structurally or functionally related to the nuclear envelope." (PMID 30781376, 2019). "Similar nuclear defects are observed in laminopathies, which are primary genetic disorders of the nuclear envelope, and include muscular dystrophies and multisystem disorders caused by mutations in lamin A/C, nesprins and other genes." (PMID 31218456, 2019). "Collectively termed laminopathies are rare genetic disorders associated with defects of the nuclear envelope largely resulting from mutations of lamin-expressing LMNA gene." (PMID 30261154, 2019). "Management of patients with EDMD and other laminopathies should include regular cardiological follow-up, considering high penetrance of LMNA mutations." (PMID 29633897, 2018). "3D artificial muscles were made by differentiating three LMNA mutant hiPSCs from patients with skeletal muscle laminopathies, referred to by their mutation as LMNA L35P, R249W, and K32del." (PMID 29669293, 2018). "Some hotspot mutations in the LMNA gene have been associated with specific types of laminopathies, as in HGPS." (PMID 29637811, 2018). "Mutations in LMNA, encoding A-type lamins, are responsible for laminopathies including muscular dystrophies, lipodystrophies, and premature ageing syndromes." (PMID 29578370, 2018). "The diagnosis of laminopathy is established in a proband by the identification of a heterozygous pathogenic variant in the LMNA gene." (PMID 29929425, 2018).
laminopathies (continued). "Hutchinson‐Gilford progeria syndrome (HGPS) is one of the most severe and devastating laminopathies linked to LMNA mutation." (PMID 29405587, 2018). "Mutations in the LMNA gene, which encodes for the nuclear lamina proteins lamins A and C, are responsible for a diverse group of diseases known as laminopathies." (PMID 30050558, 2018). "Mutations in the LMNA gene and/or alterations in its expression levels have been linked to a distinct subset of human disorders, collectively known as laminopathies, and to cancer." (PMID 29405587, 2018). "The wide spectrum of diseases within the laminopathies is attributed to different mutations in LMNA leading to various modifications in the tertiary structure of the lamin A/C proteins." (PMID 29610677, 2018). "This very large clinical spectrum associated with LMNA defects, illustrates the pathophysiological complexity of laminopathies." (PMID 29578370, 2018). "Mutations in the LMNA gene and/or alterations in its expression levels have been linked to a variety of distinct degenerative diseases, collectively known as the laminopathies, and to cancer." (PMID 29405587, 2018). "Different mutations in LMNA disrupt the integrity of the nuclear envelope, mostly in the cells subjected to mechanical stress, leading to a group of disorders known as laminopathies." (PMID 29845577, 2018). "Cardiac laminopathies, associated with mutations in the LMNA gene, encompass a wide spectrum of clinical manifestations, involving electrical and mechanical alterations of cardiomyocytes." (PMID 29929425, 2018). "LMNA mutations are associated with an array of diseases called laminopathies which include muscular dystrophy and lipodystrophy, among other diseases." (PMID 29610677, 2018). "Since mutations in LMNA gene were associated with laminopathies in 1999, numerous potential treatment options have emerged and been evaluated in mouse models." (PMID 30425656, 2018). "Previous studies have shown that LMNA mutations causing skeletal muscle laminopathies lead to defects in nuclear shape in primary patient fibroblasts, murine C2C12 myoblasts, as well as primary human myoblasts." (PMID 30405424, 2018). "All striated muscle laminopathies associated to LMNA mutation share a common denominator, the cardiac involvement, which represents the most life-threating feature of the pathology." (PMID 30425656, 2018). "In a second study, the laminopathy mutations: G489V (G449V in LMNA), N496I (N456I in LMNA), V528P (L489P in LMNA) and M553R (W514R in LMNA) were expressed only in the body wall muscles of fly larvae." (PMID 29557730, 2018). "According to the “gene expression model,” different LMNA gene mutations would affect the position or expression of different genes, leading to tissue-specific laminopathies." (PMID 29637811, 2018). "At least 15 inherited diseases called laminopathies are linked to LMNA mutations that cause the characteristic abnormal nuclear morphology." (PMID 29690642, 2018). "In the course of nearly two decades, over 400 mutations throughout the LMNA gene have been linked to various forms of laminopathies, including muscle dystrophies and partial lipodystrophies." (PMID 29517398, 2018). "In the last 15 years, ~400 mutations in the LMNA gene have been identified as causal for laminopathies, which encompass tissue-specific dystrophies affecting cardiac, cartilage, bone, skin, peripheral nerves, skeletal muscles and/or adipose tissues." (PMID 28125586, 2017). "Mutations in LMNA cause at least eight autosomal dominant phenotypes and five autosomal recessive phenotypes, termed laminopathies." (PMID 28663758, 2017). "These functions are abrogated in lamin A/C-deficient mouse embryonic fibroblasts that recapitulate the defective nuclear organization of laminopathies, featuring disruption of the actin cap." (PMID 29242553, 2017). "Mutations in the LMNA gene encoding lamin A and C (resulting from alternative splicing), emerin and nesprins cause diseases called laminopathies." (PMID 28534817, 2017).